RNF25 (ring finger protein 25)
Description:
E3 ubiquitin-protein ligase that plays a key role in the RNF14-RNF25 translation quality control pathway, a pathway that takes place when a ribosome has stalled during translation, and which promotes ubiquitination and degradation of translation factors on stalled ribosomes. Catalyzes ubiquitination of RPS27A in response to ribosome collisions, promoting activation of RNF14. RNF25 catalyzes ubiquitination of other ribosomal proteins on stalled ribosomes, such as RPL0, RPL1, RPL12, RPS13 and RPS17. Also involved in ubiquitination and degradation of stalled ETF1/eRF1. Independently of its function in the response to stalled ribosomes, mediates ubiquitination and subsequent proteasomal degradation of NKD2 (By similarity). May also stimulate transcription mediated by NF-kappa-B via its interaction with RELA/p65.
Synonyms: AO7; FLJ13906
Tractability: PROTAC: UniProt records ubiquitination sites on it; ubiquitination databases record sites on it; its protein half-life has been measured.
Gene: Protein-coding gene on chromosome 2 (218,663,866 to 218,672,006, reverse strand). Ensembl gene ENSG00000163481.
Subcellular location: Cytoplasm
Subcellular location (Human Protein Atlas): Cytosol; Actin filaments; Nucleoplasm
Pathways (Reactome):
Immune System: Antigen processing: Ubiquitination & Proteasome degradation
Gene Ontology:
Molecular function: NF-kappaB binding; protein binding; ubiquitin protein ligase activity; ubiquitin-protein transferase activity
Biological process: protein K6-linked ubiquitination; protein-RNA covalent cross-linking repair; rescue of stalled ribosome; ubiquitin-dependent protein catabolic process; protein ubiquitination
Cellular component: cytosol; cytosolic ribosome; nucleus; cytoplasm
Genetic constraint (gnomAD): Loss-of-function variants: 31 observed, 61.49 expected, observed/expected ratio (o/e) 0.5, 90% interval 0.38 to 0.68. The upper end of that interval is the gene's LOEUF score, 0.68, which puts it in group 2 of 6, group 1 being the genes least tolerant of losing a copy. Missense variants: 475 observed, 558.98 expected, observed/expected ratio (o/e) 0.85, 90% interval 0.79 to 0.92. Synonymous variants: 197 observed, 209.99 expected, observed/expected ratio (o/e) 0.94, 90% interval 0.83 to 1.06.
Homologues: Orthologues: chimpanzee RNF25 (97% identical), macaque RNF25 (90% identical), dog RNF25 (89% identical), pig RNF25 (86% identical), rabbit RNF25 (85% identical), mouse Rnf25 (82% identical), rat Rnf25 (82% identical), zebrafish rnf25 (34% identical), tropical clawed frog rnf25 (33% identical), Drosophila melanogaster CG13344 (21% identical), Caenorhabditis elegans Y53G8AR.5 (14% identical).
Diseases named in the same sentence as RNF25 in open-access papers:
RNF25 is named in the same sentence as 9 diseases in open-access papers, as found by Europe PMC text mining. Sharing a sentence is not in itself a finding about the gene and the disease. The quoted sentences say what the papers report.
hepatocellular carcinoma (3 papers, 2024 to 2025). A malignant tumor that arises from hepatocytes. "Oxidative damage can also promote the progression of hepatocellular carcinoma since it can induce the degradation of E-cadherin, mediated by ring finger protein 25 (RNF25), which is associated with tumor metastases." (PMID 39334768, 2024). "Oxidative stress can activate protein kinase A in tumor cells, lead to the phosphorylation of RING finger protein 25, and subsequently mediate E-cadherin ubiquitination and degradation, ultimately promoting hepatocellular carcinoma metastasis." (PMID 40777001, 2025). "Recent studies have shown that oxidative stress can lead to redox modifications of the protein kinase A β subunit, and in some cases, it can drive tumor metastasis by facilitating the RNF25-mediated degradation of ECAD protein in hepatocellular carcinoma." (PMID 38918844, 2024).
liver cancer (2 papers, 2024 to 2025). An epithelial or non-epithelial malignant neoplasm that arises from the liver. "The expression of RNF25 protein is negatively correlated with the protein level of ECAD in liver cancer of TCGA collected." (PMID 38286671, 2024). "As shown, RNF25 is highly overexpressed in liver cancer specifically, but not in other kinds of tumors." (PMID 38286671, 2024).
colorectal cancer (1 paper, 2025). A primary or metastatic malignant neoplasm that affects the colon or rectum. "In colorectal cancer, coactivator-associated arginine methyltransferase CARM1 methylates arginine 339 (R339) of ACSL4, promotes the binding of RNF25 to ACSL4 and its ubiquitination, inhibits ferroptosis of tumor cells, and effectively attenuates ferroptosis-related cancer immunotherapy." (PMID 40050614, 2025).
lung carcinoma (1 paper, 2018). "The involvement of RNF25 in gefitinib resistance was further validated by employing cell lines derived from tumors of lung cancer patients (PDCs) showing gefitinib resistance." (PMID 29789542, 2018). "Together, these suggests the clinical relevance of RNF25/NF-κB/ERK axis in the induction of TKI resistance in lung cancer cells." (PMID 29789542, 2018).
pancreatic cancer (1 paper, 2020). "Using multivariate Cox regression analysis, we detected eight optimal ubiquitination-related genes (RNF7, NPEPPS, NCCRP1, BRCA1, TRIM37, RNF25, CDC27, and UBE2H) and then used them to construct a risk model to predict the prognosis of pancreatic cancer patients." (PMID 33414811, 2020).
renal cell carcinoma (1 paper, 2025). "In the present study, we identify the E3 ubiquitin ligase RNF25 as a core regulator of apoptosis suppression in renal cell carcinoma via pathological NF-κB activation." (PMID 40765826, 2025). "Here, we identify the E3 ubiquitin ligase RNF25 as a key mediator of NF-κB-dependent apoptosis resistance in renal cell carcinoma cells, enabling evasion of multiple targeted therapies." (PMID 40765826, 2025).
tumor (11 papers, 2016 to 2025). "In vivo, the addition of BAY11-7082 to axitinib significantly enhanced tumor growth inhibition and apoptosis in RNF25-overexpressing SW839 xenografts." (PMID 40765826, 2025). "In summary, our study indicates that oxidative stress mediates a redox modification on the β subunit of protein kinase A, which occasionally drives tumor metastasis via the RNF25‐mediated ECAD protein degradation in HCC." (PMID 38286671, 2024). "Meanwhile, the transcriptional level of rnf25 was elevated in three separate tumor tissues more than that in paracarcinomatous tissue." (PMID 27007149, 2016). "Although widespread genomic alterations are not observed, our finding may still hold functional significance of RNF25 in tumor therapy." (PMID 40765826, 2025). "In vivo, RNF25 overexpression diminished the efficacy of axitinib in inhibiting SW839 tumor growth." (PMID 40765826, 2025). "Furthermore, the expression of ACSL4 was significantly negatively correlated with RNF25 protein expression in CRC tumor tissues of patients." (PMID 37946697, 2023). "However, gefitinib treatment in combination with RNF25 depletion significantly inhibited tumor growth compared to the treatment with either alone." (PMID 29789542, 2018). "By contrast, the primary tumor size was comparable in each group, suggesting that the PKA/RNF25/ECAD pathway is mainly involved in the regulation of tumor metastasis rather than tumor growth." (PMID 38286671, 2024). "At the early stage, ROS downregulates ECAD via RNF25‐mediated ECAD protein degradation, leading to EMT of tumor cells." (PMID 38286671, 2024). "Of the eight genes we identified, three genes (RNF7, NPEPPS, and NCCRP1) were down-regulated and the remaining five (BRCA1, TRIM37, RNF25, CDC27, and UBE2H) were up-regulated in tumor tissue compared to normal pancreatic tissue." (PMID 33414811, 2020). "There are few studies on the role of NCCRP1, RNF25, and UBE2H in cancer, but the existing research results suggest that these three genes also have the potential to become new tumor biomarkers or targets for cancer." (PMID 33414811, 2020). "Among the eight genes, five genes (BRCA1, TRIM37, RNF25, CDC27, and UBE2H) were significantly upregulated and three genes (RNF7, NPEPPS, and NCCRP1) were significantly down regulated in the tumor tissues." (PMID 33414811, 2020). "In parallel with the in vitro results, RNF25 knockdown alone did not affect tumor growth in the vehicle-treated group." (PMID 29789542, 2018). "Western blot analysis and TUNEL assays showed that axitinib treatment induced a higher level of tumor cell apoptosis in control tumors but not in those with high RNF25 expression, indicating that elevated RNF25 levels promote axitinib resistance through anti-apoptotic mechanisms." (PMID 40765826, 2025).
cancer (4 papers, 2020 to 2025). A tumor composed of atypical neoplastic, often pleomorphic cells that invade other tissues. "To simulate patient conditions, we stably overexpressed RNF25 in HK-2 normal kidney cells and treated them with a range of small molecule inhibitors targeting various cancer pathways." (PMID 40765826, 2025). "In conclusion, our study reveals that the E3 ubiquitin ligase RNF25 plays a critical role in promoting NF-κB-driven resistance to apoptosis in cancer cells, facilitating escape from various targeted treatments." (PMID 40765826, 2025). "We further analyzed RNF25 expression levels across various cancer types using The Cancer Genome Atlas (TCGA) datasets and found that RNF25 was elevated in most cancers." (PMID 40765826, 2025). "Our findings indicate that RNF25 is overexpressed in various cancer types and contributes to resistance against various small molecule inhibitors, particularly apoptosis-inducing agents like gemcitabine and docetaxel, suggesting a previously unexplored mechanism underlying drug resistance." (PMID 40765826, 2025). "Pan-cancer analyses from cBioPortal reveal no recurrent mutations, deletions, or amplifications of RNF25 across most malignancies." (PMID 40765826, 2025). "Our study highlights RNF25 as a druggable regulator of therapy resistance via NF-κB signaling modulation and supports BAY11-7082 as a potential therapeutic approach to overcome apoptosis resistance in cancer." (PMID 40765826, 2025).
RNF25 also shares sentences with these, for which no sentence is quoted: multiple myeloma (1 paper).